IL10 (interleukin 10)
Diseases named in the same sentence as IL10 in open-access papers (continued):
Sharing a sentence is not in itself a finding about the gene and the disease.
Behcet disease (23 papers, 2012 to 2025). A chronic, relapsing, multisystemic vasculitis characterized by mucocutaneous lesions, as well as articular, vascular, ocular and central nervous system manifestations. "Low IL10 expression has been linked to the etiology of inflammatory and autoimmune illnesses including Behcet’s disease (BD), and polymorphisms in multiple immunoregulatory genes have been linked to an increased risk of developing BD." (PMID 38822340, 2024). "Increased production of cytokine IL-10 (encoded by the IL-10 gene) mediated by IFN-alpha was a key finding in an in vitro study of PBMCs derived from Behcet’s disease patients." (PMID 32404512, 2020). "Low C-C chemokine receptor 1 (CCR1) and interleukin (IL)-10 expression is associated with risk of Behçet’s disease (BD)." (PMID 29895319, 2018). "This SNP has been found to be associated with Behcets disease and down regulates IL10 expression in juvenile rheumatoid arthritis." (PMID 25941808, 2015). "Association analysis of clinical subclasses with IL10 c.-819T SNP in patients with Behçet’s disease." (PMID 24151497, 2013). "Behcet's disease is associated with a variant (rs1800871) that lies near the IL-10 promoter, adjacent to BRG1, STAT6 and CBP binding." (PMID 22336179, 2012). "Epidemiological studies have demonstrated that interleukin-10 (IL-10) polymorphisms may be associated with the development of Behcet's disease (BD)." (PMID 32656270, 2020). "For example, Behçet’s disease is correlated with elevated levels of IFN-γ and reduced levels of IL-10, while VKH disease is linked to high levels of both IL-10 and IFN-γ." (PMID 40433375, 2025). "One year later, GWAS studies including larger cohorts were performed revealing two loci associated with Behçet's disease at GWAS level of significance: interleukin 23 receptor (IL23R) and the interleukin 10 (IL10)." (PMID 33644100, 2021). "And their study found that the expression level of IL-10 gene was significantly decreased in blood samples from patients with Behçet's disease, mainly due to the high methylation of the IL-10 promoter region resulting in decreased mRNA expression levels." (PMID 32582189, 2020). "Behçet’s disease (BD) susceptibility had been associated with single-nucleotide polymorphisms (SNPs) in IL23R–IL12RB2, IL10, STAT4, or ERAP1 locus in Japanese, Turkish, Chinese, and other populations, but not in a Korean genome-wide association study (GWAS)." (PMID 29017598, 2017). "This last point underlines the presence of different pathophysiological mechanisms implicated in Behçet disease and suggests that arginases, with TGF-β and IL-10, are part of the regulatory pathways of immune disorders during Behçet disease." (PMID 25692069, 2015). "The IL-10 gene locus has multiple GWAS hits, including association with inflammatory and autoimmune disorders, including Behcet’s Disease (rs1518111, p = 4e-18), and with numerous eQTLs specific for IL-10 mRNA expression in GTEx, distributed over a large genomic region." (PMID 29847580, 2018). "IL-10 is closely related to the occurrence and development of various oral mucosal diseases, such as ROU, oral lichen planus, Behcet’s disease, and pemphigus." (PMID 33995016, 2021). "Behçet's syndrome is a rare, systemic inflammatory vascular disorder with unknown etiology, although associations with HLA-B*51 and several non-MHC loci including IL23R-IL12RB2 and IL-10 have been described." (PMID 33996677, 2021).
bipolar disorder (23 papers, 2014 to 2024). A disorder of the brain that causes unusual shifts in mood, energy, activity levels and the ability to carry out day-to-day tasks. "Abnormal levels of cytokines, including TNF-α, IL-8, and IL-10, are significantly associated with IBS and bipolar disorder symptoms, indicating that IBS and bipolar disorder share similar pathophysiological mechanisms." (PMID 38352653, 2024). "In contrast, another population-based study showed significantly higher serum IL-6 and IL-10 levels in patients with MDD or bipolar disorder (BD) than in a healthy control group." (PMID 38646609, 2024). "However, the authors did not assess the serum level of inflammatory markers in the euthymic state, the results showed a significant decrease in IL6 level during bipolar depression and severe bipolar mania and decrease in IL10 level during bipolar depression." (PMID 38036661, 2024). "In addition, the decrease of the ratios of IL-6/IL-10 and IL-17/IL-10 found in this study also suggests that immune-inhibition is prominent in bipolar depression, especially in severe BD." (PMID 36741577, 2022). "However, the anti-inflammatory cytokine IL-10 was only significantly elevated in first-episode bipolar disorder, consistent with a previous meta-analysis." (PMID 29803226, 2018). "Based on published values, the IL-6/IL-10 ratio is 1:18 in mania and 2:44 in bipolar depression." (PMID 25202283, 2014). "Unfortunately, we didn’t have any samples from patients in hypomania to compare and confirm a relationship between IL-10 level and B cell percentage but we believe that the increase of B cell percentage observed ex vivo in these patients could be explained by high level of IL-10." (PMID 30971748, 2019). "Serum levels of IL-6, IL-10, TNF-α, and MDA were also improved in patients with bipolar disorder treated for 8 weeks with a specific mix of lactic probiotics." (PMID 37764004, 2023). "A meta-analysis of 30 studies that included 1351 individuals with bipolar disorder and 1248 controls found that plasma/sera levels were elevated for IL-6, TNF-α, soluble IL-2 receptor, IL-4, IL-10, IL-1 receptor antagonist, and soluble TNF receptor-1." (PMID 29803226, 2018). "The reason for this discrepancy is unclear, although similar findings have been previously reported by another group where only thalamic and not midbrain SERT availability was correlated with IL-10 in bipolar disorder." (PMID 31178771, 2019). "Levels of IL-2, IL-4, IL-10 and IFN-γ were not significantly different from controls in either mania or euthymia, but current study numbers mean no conclusions can be reached regarding levels in bipolar depression; further studies are required." (PMID 30113291, 2018).
cardiac hypertrophy (23 papers, 2012 to 2025). "Their study revealed that these exosomes modulate the expression of the anti-inflammatory cytokine interleukin-10 (IL-10), thereby alleviating myocardial hypertrophy, reducing cardiac inflammation, and mitigating fibrosis." (PMID 40642081, 2025). "Receptor-mediated IL-10 signalling in the heart controls myocardial hypertrophy in response to excessive pressure stimulation." (PMID 39200761, 2024). "In this study we sought to address an important question as to how IL-10 reduced cardiac hypertrophy." (PMID 33192505, 2020). "The aim of this study was to investigate the effects of the ablation of Il-10-r1 gene during pathological cardiac hypertrophy in mice." (PMID 33192505, 2020). "Cyclophosphamide (CTX) induces myocardial fibrosis and cardiac hypertrophy, as well as changes in the expressions of several cytokines, such as interleukin (IL)-2, IL-10, IL-6, and TNF-α, which can further facilitate the occurrence and development of AF." (PMID 30386232, 2018). "Our data supports previous evidence that signaling modulated by IL-10 and its receptor may become a potential target to control pathological cardiac hypertrophy." (PMID 33192505, 2020). "Subsequently, we asked whether IL-10 was necessary for the abatacept-mediated effects on cardiac hypertrophy." (PMID 28262700, 2017). "In addition, serum IL-10 overexpression can attenuate ventricular hypertrophy via the STAT3 pathway." (PMID 27936072, 2016). "Likewise, IL-10−/− mice display normal cardiac hypertrophy, but exaggerated vascular fibrotic remodeling post-TAC." (PMID 22916095, 2012). "The RT protocol was able to attenuate cardiac hypertrophy, left ventricular collagen volume fraction and reduced IL-6 and the ratio of TNF-α/IL-10; also, there was increased IL-10 in CHF rats." (PMID 25340545, 2014). "Finally, CTX use leads to myocardial hypertrophy, myocardial fibrosis, and changes in the expressions of some cytokines, such as IL-1β, TNF-α, and IL-10, which are likely to promote AF development." (PMID 30386232, 2018). "The present study found that CTX produced massive change including cardiac hypertrophy, fibrosis, heart edema with inflammatory cell infiltration and the expression change of several cytokines such as IL-1β, TNF-α and promoting IL-10, which were antagonized by BAE." (PMID 26133371, 2015). "Cardiac hypertrophy, as assessed by HW: BW ratio, was not significantly different in IL-10−/− and wild-type mice after TAC (7.7±2.0 and 7.1±1.3, respectively, P = 0.596)." (PMID 22916095, 2012). "Evidence suggests that IL-10 potentially reduces pathological hypertrophy, hypothesized to occur through signaling via the IL-10 receptor (IL10R) in the heart, exerting a protective role in reducing cardiac hypertrophy." (PMID 40257974, 2025). "Based on the evidence that IL-10 potentially reduces pathological hypertrophy, it was hypothesized that signaling via the IL-10 receptor (IL10R) in the heart produces a protective role in reducing cardiac hypertrophy." (PMID 33192505, 2020). "In addition, resistance training was able to reduce myocardial hypertrophy (P<0.05), left ventricular total collagen volume fraction (P<0.01), IL-6 (P<0.05), and TNF-α/IL-10 ratio (P<0.05), as well as increasing IL-10 (P<0.05) in chronic heart failure rats when compared to the S-CHF group." (PMID 25340545, 2014).
chronic obstructive pulmonary disease (23 papers, 2018 to 2025). A chronic and progressive lung disorder characterized by the loss of elasticity of the bronchial tree and the air sacs, destruction of the air sacs wall, thickening of the bronchial wall, and mucous accumulation in the bronchial tree. "At the same time, it has been proved that the decrease of IL-10 level is a risk factor for chronic obstructive pulmonary disease (COPD)-PH." (PMID 38529271, 2024). "Compounds 58 and 145–149 had inhibitory effects on the IL-6 expression and promoting effects on the IL-10 expression in the serum of rats induced by chronic obstructive pulmonary disease (COPD) caused by cigarette smoking." (PMID 33260848, 2020). "Several researches had shown that miR-155HG regulated the expression of TNF-α, IL-1β, IL-10, and IL-12, together with GM-CSF-mediated polarization of M1/M2 macrophages in the progression of chronic obstructive pulmonary disease (COPD)." (PMID 35434143, 2022). "We demonstrate that alveolar macrophages display high resemblance to IL10 activation, but show a drop in IFNγ signature in chronic obstructive pulmonary disease patients." (PMID 31921150, 2019). "High significance was found for ‘pathogen induced cytokine storm signaling’, ‘airway pathology in chronic obstructive pulmonary disease’ ‘IL-10 signaling' and multiple pathways related to ‘IL-17 signaling’ and ‘macrophage classical activation signaling pathway’." (PMID 38839796, 2024). "In patients with chronic obstructive pulmonary disease (COPD), a significant decrease in the number of B cell subsets with a reduced ability to produce anti‐inflammatory IL‐10 worsens the condition." (PMID 40760821, 2025). "In chronic obstructive pulmonary disease (COPD), IL-35 levels correlate with disease characteristics alongside IL-17 and IL-10, positioning IL-35 as a potential biomarker for disease monitoring and therapeutic targeting." (PMID 40869939, 2025). "This study aims to explore the correlation between high-sensitivity C-reactive protein (hs-CRP), interleukin-6 (IL-6), interleukin-10 (IL-10), endothelin-1 (ET-1), and chronic obstructive pulmonary disease combined with pulmonary hypertension (COPD-PH)." (PMID 35186226, 2022). "Human pulmonary cDC2s mediated IL-10 producing Treg, which suppressed chronic obstructive pulmonary disease (COPD), via IL-10, IL-27 and inducible T cell costimulator ligand (ICOSL)." (PMID 31640263, 2019). "In this study, we investigated the diagnostic utility of a plasma interleukin panel comprising IL-6, IL-10, IL-8, and IL-1RA to distinguish early-stage NSCLC from healthy individuals and patients with chronic obstructive pulmonary disease (COPD)." (PMID 41303495, 2025). "Measuring 30 cytokines in 936 sputum samples from patients with chronic obstructive pulmonary disease, we observed significant increases (IL-17A, TNF-α, IL-1β, IL-10) between stable and exacerbation states." (PMID 38836471, 2024). "Potato extract has been shown to increase the expression of IL-10 and reduce the expression of TNF-α in serum and lung tissues of rats with cigarette smoke-induced chronic obstructive pulmonary disease." (PMID 29495317, 2018). "Furthermore, another study on patients with chronic obstructive pulmonary disease by Rubing Mo and collaborators found that LPS induces lncRNA GAS5 expression and release of IL-2, IL-6, IL-10, and TNF-α." (PMID 37047453, 2023).
glaucoma (23 papers, 2012 to 2025). Increased pressure in the eyeball due to obstruction of the outflow of aqueous humor. "The anti-inflammatory cytokines IL-4 and IL-10 may play a compensatory role early in glaucoma, prior to functional transport loss and RGC death, and could induce alternative activation and polarization of M2 microglia." (PMID 33669765, 2021). "The MR analysis genetically predicted that the levels of six distinct circulating inflammatory cytokines might be causally linked to the risk of these blinding eye diseases, including MIG for glaucoma, IL-1ra, IL-6, IL-10 and PDGFbb for cataract, and MIG and HGF for macular degeneration." (PMID 38327497, 2024). "While the majority of changes we observed were in pro-inflammatory mediators, our results suggest that anti-inflammatory cytokines may play a compensatory role early in glaucoma prior to transport loss, as evidenced by early elevations in retinal IL-5 and IL-10." (PMID 26376776, 2015). "CSIF:TGIF(IL-10) is a key regulator of the systemic anti-inflammatory responses and functions to protect glaucoma patients from the persistent low-grade inflammatory state causing eye tissue damage." (PMID 38540099, 2024). "Conversely, unlike previous data obtained in MCE rodent models, no change in the protein expression level of the anti-inflammatory cytokine IL-10 was detected after glaucoma induction." (PMID 38337691, 2024). "In a glaucoma mouse model, increased expressions of inflammatory cytokines, including interferon-γ, IL-6, IL-4, IL-10, and IL-1β were found." (PMID 37744880, 2023). "Pro-inflammatory cytokine IL-10 concentration has been found to be higher in the AH of patients with primary open-angle glaucoma." (PMID 37511830, 2023). "IL-10 levels were higher in the glaucoma group compared to the control group (p < 0.05, unpaired t-test)." (PMID 37511830, 2023). "A total of 6 cytokines were found significantly elevated in glaucoma samples compared to controls, which include IL-10, IL-12, IFN-γ, IFN-α, IL-9, and CXCL-9." (PMID 22355254, 2012). "The results suggest that IL-18 and PDGF-BB may be upstream causes of AMD; Genetically predicted RANTES had protective effect on glaucoma; IL-10 had protective effect on DR." (PMID 40687727, 2025). "Notably, the aqueous humor of patients with glaucoma has higher concentrations of cytokines, such as IL-4, IL-6, IL-8, IL-10, vascular endothelial growth factor, and interferon-α, compared to healthy individuals." (PMID 38651060, 2024). "Furthermore, individuals diagnosed with glaucoma have been observed to exhibit elevated levels of various inflammatory cytokines, including IL-9, IL-10, IL-12, IFN-α, and MIG." (PMID 38327497, 2024). "Moreover, in MCE-injected animals, an ACE oil-enriched diet upregulated the expression of IL-10, suggesting the triggering of some protective mechanism in response to glaucoma induction." (PMID 38337691, 2024). "IL-10 is involved in fibrosis and described as a tissue remodeling-related inflammatory mediator, highlighting its potential pathophysiological mechanism in glaucoma." (PMID 37511830, 2023). "Based on these findings, it might be suggested to assess whether the IL-10 polymorphisms can be influential on fibrillar amyloid deposition in PEX and PEXG glaucoma." (PMID 32050932, 2020). "In primary open-angle glaucoma (POAG), serum IL-6/IL-10 ratio contributed to discriminate the disease progression." (PMID 36371539, 2022). "Among these cytokines, the median concentrations of IL-10 (p=0.050), IL-12 (p=0.003), IFN-γ (p=0.002), IFN-α (p=0.034), IL-9 (p=0.032), and CXCL9 (p=0.006) were also significantly higher in the glaucoma group." (PMID 22355254, 2012). "Surprisingly, CSIF:TGIF(IL-10) levels were higher among patients with severe glaucoma compared with patients having mild-to-moderate glaucoma, although this variation was not statistically significant." (PMID 38540099, 2024).
glaucoma (continued). "Additionally, a glaucoma animal model, DBA2J, developed PAS and iris atrophy with age, and the AqH levels of IL-1β, IL-6, IL-10, IFN-γ, TNF-α, MCP-1 and GM-CSF at 50 weeks were significantly higher than those at 8 weeks." (PMID 34830147, 2021). "In the DBA2J mice, an experimental glaucoma model that developed PAS at 50 weeks, the AqH levels of IL-2, IL-6, IL-10, IFN-γ, tumor necrosis factor-α, MCP-1 and granulocyte-macrophage colony-stimulating factor (GM-CSF) significantly increased at 50 weeks compared to 8 weeks (p ≤ 0.021)." (PMID 34830147, 2021). "The development of inflammation in AMD, diabetic retinopathy, retinitis pigmentosa, retinopathy of prematurity, and glaucoma seems to be regulated by interleukin-1 (IL-1) family members, as well as tumor necrosis factor alpha (TNF-α) and its counterpart interleukin-10 (IL-10)." (PMID 31973128, 2020). "Aqueous obtained from the glaucoma patients showed increased concentration of interleukin (IL)-9 (p=0.032), IL-12 (p=0.003), interferon (IFN)-α (p=0.034), IFN-γ (p=0.002), monokine induced by interferon-gamma (MIG or CXCL9) (p=0.006), and IL-10 (p=0.050), compared to the cataract group." (PMID 22355254, 2012).
Glucose intolerance (23 papers, 2011 to 2025). Glucose intolerance (GI) can be defined as dysglycemia that comprises both prediabetes and diabetes. "TMAO can exacerbate glucose intolerance, promote the expression of proinflammatory factors, and decrease the levels of anti-inflammatory cytokine, IL-10, in adipose tissue." (PMID 40863123, 2025). "Notably, injection of IL-10-treated SVFs induced Akt phosphorylation in the livers of Leprdb/db mice following insulin administration and reduced glucose intolerance." (PMID 39125659, 2024). "Interestingly, glucose intolerance reduces IL-10 signaling efficiency, resulting in increased TNF-α production." (PMID 37313404, 2023). "At the same time, anti-inflammatory IL-10 inhibited HFD-induced weight gain, IR and glucose intolerance." (PMID 25781614, 2015).